LINC01391 (long independently transcribed non-coding RNA 1391)
Gene: Long non-coding RNA gene on chromosome 3 (138,935,189 to 138,944,020, reverse strand). Ensembl gene ENSG00000244578.
Diseases named in the same sentence as LINC01391 in open-access papers:
LINC01391 is named in the same sentence as 1 disease in open-access papers, as found by Europe PMC text mining. Sharing a sentence is not in itself a finding about the gene and the disease. The quoted sentences say what the papers report.
tumor (1 paper, 2020). "Furthermore, we suggested an important role for LINC01391 in aerobic glycolysis and tumor progression of GC via competitively binding and repressing miR-12116 to facilitate CMTM2 expression in GC." (PMID 33033510, 2020).